IFNG (interferon gamma)
Diseases named in the same sentence as IFNG in open-access papers (continued):
Sharing a sentence is not in itself a finding about the gene and the disease.
tumor (continued). "To evaluate the dynamic expression of AdIFNγ in vivo, we measured the levels of hIFNγ in tumor and blood samples collected from nude mice carrying CNE-2 NPC xenografts on days 1, 3, 5 and 7 after intratumoral injection with Ad-IFNγ." (PMID 23272637, 2012). "Since it is known that a broad spectrum of tumor cells lack MHC presentation and show hypermethylation of IFNγ target genes such as CIITA, we treated RMS cells with the demethylation reagent 5′aza 2′deoxycytidine." (PMID 22919516, 2012). "The results showed that the expression of IFNγ and TNFα in HCC tissues, especially at the edge of tumor, was higher than in normal liver tissues." (PMID 22952657, 2012). "IL-12 stimulates T lymphocytes and natural killer cells to release interferon gamma (IFN-γ), which has been shown with the capability to inhibit tumor growth, angiogenesis, and metastasis both in rodents and human." (PMID 22808019, 2012). "CXCL9 is produced in the tumor-microenvironment in response to IFNγ production, and can attract CXCR3+ T cells into the tumor." (PMID 22359647, 2012). "An increased expression of mouse-derived cytokines IFNG and interleukin 7 was found in VEGFA165 tumours, both described to induce SMAD7 expression." (PMID 22045186, 2011). "To do this, we treated tumor-bearing mice with media (mock), Sin/LacZ, Sin/IL12, Sin/IL12 + anti- IFNγ (to block IFNγ activity), or Sin/IL12 + anti-CD122 (to deplete NK cells)." (PMID 21674047, 2011). "Our results show that endothelial and/or stromal cells within the tumour express higher levels of mouse-specific cytokines (MCSF, IFNG, IL5, IL7 and CXCL9) in VEGFA165 tumours compared with control tumours." (PMID 22045186, 2011). "The use of the transwell barrier reversed the ability of WSX1 to reduce T cell number and IFNγ production in T cells, suggesting that WSX1-positive tumors initiate immunosuppression via a direct tumor/immune cell contact-dependent manner." (PMID 21559505, 2011). "By day 7, IFNγ, CSF2, CXCL10, GZMB, PTGS2, TNFα, CD80, CCL22, IL12a, IL13, IL1b, IL6, NOS2, and CTLA4 were significantly upregulated in the tumor-bearing mice bladders and AGTR2 and GATA3 were downregulated." (PMID 22013484, 2011). "Growing evidence suggests that various types of human tumor cells express IDO, and inflammatory mediators, especially interferon-γ (IFNγ), have the specific ability to induce IDO expression." (PMID 22013481, 2011). "The strong cytotoxic activity of our UCB-derived NK cells against various tumor cell lines as well as the cytolysis of primary AML cells were displayed by specific lysis, CD107a-mediated degranulation and the production of IFNγ." (PMID 20169160, 2010). "Targeted delivery of ultra-low doses (picogram range) of a recombinant IFNγ-CNGRC conjugate (IFNγ-NGR) to tumor vasculature overcomes major counter regulatory mechanisms and delays tumor growth in mice." (PMID 27713313, 2010). "After activation with interferon-gamma (IFN-γ) ex vivo, macrophages are capable of selectively lysing tumour cells." (PMID 20529333, 2010). "We found that greater percentage of tumor-infiltrating P14IL-2 (0 h) effector T cells produced granzyme B and IFNγ than P14 and P14IL-2 (24 h) effector T cells (granzyme B: 47.13% vs. 18.59% vs. 30.73%, IFNγ: 35.26% vs. 27.29% vs. 27.26%)." (PMID 19901991, 2009). "We have reported that r-hu-IFNγ treatment exerts anti-proliferative effects in vitro on NPC cells, and leads to a profound anti-tumor effect in vivo." (PMID 19216804, 2009). "We previously reported that selection of the radioresistant tumor nu61 by in vivo fractionated IR was accompanied by overexpression of the IFN/STAT1 pathway and combined resistance to IR, IFNα, and IFNγ." (PMID 19503789, 2009). "Previously, we showed that stable knockdown of STAT1 in IR-resistant and IFNα/IFNγ-resistant tumor cells led to radiosensitization, suggesting that STAT1 is one important mediator in the IR-resistant tumor phenotype." (PMID 19503789, 2009).
tumor (continued). "Strikingly, VA Qu Spez-treated DCs activated tumor antigen specific CTL clone as analyzed by the secretion of cytokines TNF-α and IFNγ." (PMID 18533025, 2008). "We did however observe that IFNγ−/− mice, when challenged with MCA, demonstrate a reduction of the percentage of CD4+FOXP3+ Tregs within tumours and TDLN." (PMID 17565340, 2007). "In this inflammatory milieu IFNγ most likely will be produced, resulting in the local induction of MHC II expression by tumour cells, which would be in accordance with the data presented in this paper." (PMID 12569387, 2003). "The aim of this study was to investigate mechanisms of anti-tumour activity and necrosis induced by combinations of tumour necrosis factor alpha (TNF-alpha) and interferon gamma (IFN-gamma)." (PMID 7577463, 1995). "In addition, NP-APC11 treatment, in contrast to NP-APC11M treatment, significantly increased the expression of the effector cytokines IFNγ and TNFα in CD8+ T cells, highlighting its role in enhancing the anti-tumor immune response." (PMID 41486293, 2026). "This signaling cascade results in the transcriptional alteration of genes critical for T cell effector functions, including the downregulation of interferon-gamma (IFN-γ) and granzyme B, while potentially upregulating inhibitory receptors like PD-1, thereby facilitating tumor immune evasion." (PMID 41601691, 2026). "We find that tumor control does not depend on CD8+ T cells or tumor cell MHC expression but instead requires IFNγ-producing CD4+ T cells (Th1s) that are primed by dendritic cells in lymph nodes." (PMID 42102812, 2026). "This study also suggested that innate immune protection against tumor cells in the absence of adaptive immunity was mediated by NK cells and their secretion of IFNγ." (PMID 41315764, 2026). "For example, NK cells in early, but not late, tumors expressed IFNγ, which activates macrophages and suppresses tumor growth, which was sensed by a broad range of tumor cell subtypes and most immune cells." (PMID 41315764, 2026). "Single-cell analysis identified a distinct population of inflammatory monocytes that were enriched for an IFNγ response signature in CD40 agonist-treated tumors, suggesting that these cells may be important for tumor control." (PMID 41676732, 2026). "Also, in a murine syngeneic tumor model, inhibition of BRAF signaling enhanced production of IFNγ and TNFα and increased MHC class I and II expression on tumor cells." (PMID 41514118, 2026). "Of note, the observed antitumor response of γδ TILs did not depend on pretreating tumor digests with hrIFNγ, suggesting that γδ TILs do not react to IFNγ response genes." (PMID 40897471, 2025). "Although not statistically significant, a higher trend in IFNγ production was observed in the microtumor-alone condition following anti-PD-1 treatment, suggesting a potential anti-tumor response from the TILs population." (PMID 40873566, 2025). "IFNγ operates through a cysteine/glutamic acid reverse transport system, solute carrier family 7 member 11(SLC7A11) and SLC3A2, that targets the surface of tumor cell membranes." (PMID 39820341, 2025). "Altogether, our results suggest that IFNγ is critical for promoting the growth and the expression of CXCL5 of 3D tumor cells and that TNFα may be a downstream effector molecule of LPS-stimulation." (PMID 40050422, 2025). "IFNG is upstream of STAT1 and activates its anti-tumor effects by binding to IFNGR1." (PMID 40659662, 2025). "Mechanistically, tumor-derived transforming growth factor-beta (TGF-β) plays a central role in dampening NKT cell effector functions by downregulating activating receptors and impairing cytokine production, particularly IFNγ." (PMID 40868256, 2025). "All these results suggest that Ad-E7 used in combination therapy confers an ability to the immune system to limit tumor growth by lowering Treg and MDSC levels while minimizing tumor size via invasion of CD8 T-cells and their corresponding release of interferon gamma." (PMID 40006746, 2025).
tumor (continued). "Further studies revealed that IFNγ release, rather than perforin, is the primary mechanism of tumor killing by anti-CD19 CD4+ CAR T cells." (PMID 40995371, 2025). "Their activation requires tumor antigens presentation by dendritic cells (DCs), co-stimulation signals (e.g., CD28-B7), and pro-inflammation cytokines [e.g., interleukin (IL)-12, interferon-gamma (IFN-γ)], leading to clonal expansion and cytotoxic effector functions acquisition." (PMID 41268548, 2025). "Moreover, RGD + aPD-1 treatment promoted IFNγ production by tumor-infiltrating T cells, including CD8+ effector T cells, and elevated IFNγ intratumoral levels." (PMID 40281508, 2025). "Given that not all individual cancer cells in human tumours are unresponsive to IFNγ, we used a B16-OVA WT and IFNγRKO admix model whereby tumour cells are tagged in ZsGreen or mCherry, or vice versa, and mixed in equal proportions prior to engraftment." (PMID 39746898, 2025). "In vitro experiments indicated that interferon gamma (IFNγ), a key immune cytokine in MSI tumours, downregulates FABP1 expression, while activation of PPARγ (with rosiglitazone) can restore it, suggesting a regulatory loop influenced by inflammatory signalling." (PMID 41149452, 2025). "Specifically, IFNγ and TNFα were identified as key upstream regulators that dictate the activation status of eosinophils facilitating CD4+ and CD8+ T cell infiltration and anti-tumor immunity." (PMID 40050933, 2025). "Moreover, high TMB was associated with increased T cell infiltration and exhibited a distinct gene signature, which highlights the potential of IFNG, KEAP1, and PHKG2 as predictive markers for T cell infiltration and the tumor microenvironment status in OV." (PMID 40744688, 2025). "Our recent study highlights the role of the inflammatory microenvironment, particularly IFNγ signaling, in driving the silencing of TFF1, a well-established tumor suppressor in gastric carcinogenesis, with the transcription factor C/EBPβ playing a key role in this process." (PMID 41573568, 2025). "Furthermore, the tumor microenvironment was completely reshaped toward anti-tumor inflammatory cells, as illustrated by changes in the CD8 to CD4 ratio and IFNγ-producing CD8+ T cells to T-regs ratio in the huCC49-IL-2-treated tumors and lymphoid organs." (PMID 40361381, 2025). "Tumor cells that lack responsiveness to IFNγ signaling often exhibit impaired or absent MHC class I antigen presentation, facilitating immune evasion." (PMID 41584608, 2025). "Analysis of metastatic CRC samples mirrored these findings: STAT1-high tumors exhibited more immunogenic microenvironments, characterized by higher tumor and stromal MHC-I/PD-L1 expression and increased TILs, along with transcriptomic signatures of IFNγ, HLA-A/E/G, and cytotoxic effectors." (PMID 41293269, 2025). "Studies have demonstrated that IFNG enhances immune cell infiltration by directly activating CD8+ T cells and modulating other components of the tumor microenvironment, such as CXCLs, MHC-I, and galectin-9 (Gal-9), while counteracting cancer-associated fibroblast (CAF)-mediated immunosuppression." (PMID 41368643, 2025). "CTLs also produce cytokines such as interferon-gamma (IFN-γ) and tumour necrosis factor-alpha (TNF-α), which further promote antitumour immune responses by enhancing the activation of other immune cells and modulating the tumour microenvironment." (PMID 39537767, 2025). "Further work revealed that tumour-infiltrating CD8+ T cells exposed to oxidized phospholipid-containing oxLDL become dysfunctional, resulting in reduced production of tumour necrosis factor-alpha (TNFα) and interferon-gamma (IFNγ)." (PMID 40730233, 2025). "Detection of killer cytokines IFNG/IFN-γ, TNF/TNF-α, and GZMB secreted by CD8+ T cells revealed that reduced circGRAMD4 expression relieved tumor cell-induced immunosuppression, whereas increased circGRAMD4 expression suppressed the production or release of these immune factors." (PMID 40373256, 2025).
tumor (continued). "This divergence in the dynamics of circulating vs. tumour IFNγ signatures likely reflects therapy-induced T cell infiltration and localised immune remodelling in the tumour microenvironment – features not captured in the circulation." (PMID 41291768, 2025). "The expression of 127aa could result in different levels of metabolic excretion in tumor cells, followed by stepwise changes in metabolic pathways in NK cells and, in turn, NK dysfunction, as shown by the decreases in CD56, IFNγ, and GZMB expression." (PMID 39402211, 2025). "Following coculture with E0771-Her2 tumor cells, A1R CAR T cells exhibited significantly increased production of IFNγ and TNF and increased expression of effector related genes PD-1 (Pdcd1), TIM-3 (Havcr2), Gzmb and Irf4 compared to control and A3R CAR T cells." (PMID 40610421, 2025). "Upon antigen recognition, CTLs execute their cytotoxic functions by secreting granzyme B and perforin, increasing the synthesis and release of cytokines such as interferon-gamma (IFN-γ) and tumor necrosis factor-alpha (TNF-α) and inducing tumor cell apoptosis via the FasL/Fas pathway." (PMID 40458394, 2025). "Thus, despite low MHC-I expression and insensitivity to IFNγ, the control of growth and selection of IFNγRKO tumours remained CD8+ T cell- and IFNγ-dependent." (PMID 39746898, 2025). "The increase in CD107a expression and intracellular positivity for IFNγ in CD8+ T cells, together with the labeling of tumor cells with an appropriate probe, indicate that T cells can activate effector functions and perforin release upon interaction with CRC organoids." (PMID 40136707, 2025). "Furthermore, IFNG+ T cells activate cytotoxic T cells through CLEC2B/C/D-KLRB1 signaling, enhancing their tumor-killing capacity." (PMID 41203637, 2025). "Furthermore, interferon-gamma (IFN-γ), a type II interferon with antiviral, antitumor, and immunomodulatory properties, is produced by immune cells such as CD4+ and CD8+ tumor-specific T lymphocytes." (PMID 40005446, 2025). "The few CD4+ T cells recruited to tumours were mainly Tregs and as such, they did not substantially contribute to IFNγ production." (PMID 39746898, 2025). "Taken together, our findings suggest that the balance between IL-17 and IFNγ in Th17 cells, shaped by vitamin D3 signaling and OPN receptor engagement, may determine whether Th17 cells exert pro- or anti-tumor effects." (PMID 40894304, 2025). "Furthermore, flow cytometric analysis of tumor-infiltrating lymphocytes revealed that Vin-induced increases in CD8+ T cell infiltration, as well as the proportions of GZMB+ and IFNγ+ CD8+ T cells, were abolished in both ATF3- and IL-24-deficient tumors." (PMID 40866941, 2025). "Notably, preclinical models demonstrate that OVs can induce tumor cells to re-express MHC-I and enhance dendritic cell cross-presentation by carrying immunomodulatory genes such as GM-CSF or interferon-gamma (IFN-γ), exemplified by T-VEC’s GM-CSF engineering." (PMID 41425703, 2025). "It appears that upon initial antigen encounter, effector-polarized CAR-T cells, particularly those with CD28 co-stimulation, produce substantial IFNγ, which enhances ICAM-1 expression on tumor cells and facilitates subsequent CAR-T cell infiltration into tumor tissue." (PMID 41154636, 2025). "Tumor cells in high entropy MRs were also significantly more likely to have nuclear IRF1 (interferon regulatory transcription factor 1), suggesting that they were exposed to interferon-γ (IFNγ)." (PMID 40667360, 2025). "Cytotoxicity in IFNG-expressing tumour cells was more pronounced at 24 h, but no longer statistically significant by 72 h." (PMID 41366257, 2025).
tumor (continued). "Induced by lipopolysaccharide (LPS) and interferon-gamma (IFN-γ), M1 macrophages recognize tumor cells through surface antigens and execute their functions by producing reactive oxygen species (ROS), inducible nitric oxide synthase (iNOS) coupled with the production of pro-inflammatory cytokines." (PMID 40433363, 2025). "As CD8+ T cells and IFNγ are crucial mediators in fighting cancer, these results support the hypothesis that BOC1 may alter the tumor microenvironment, making it hostile to tumor growth." (PMID 40904466, 2025). "Mechanistically, ROS1-mutant tumors displayed an immunosuppressive tumor microenvironment characterized by diminished CD8+ T cell infiltration, attenuated interferon-γ signaling, and downregulation of immune-related genes (CXCL9, CXCL10, IFNG, PD-L1)." (PMID 40873541, 2025). "Their unique ability to recognize and eliminate tumour cells without prior sensitization, coupled with the secretion of pro-inflammatory cytokines such as interferon-gamma and tumour necrosis factor, position them as promising agents in cancer therapy." (PMID 40060948, 2025). "We demonstrate that SLC7A5 deletion affected T cell activation, expansion and survival, and reduced IFNγ and granzyme B expression, thus controlling aGVHD, but without effect on tumor growth." (PMID 40399490, 2025). "Furthermore, GSEA analysis showed reductions in genes related to anti-tumor immune responses including the IL-2/STAT5, the interferon-gamma and the PI3K/AKT/mTOR signaling." (PMID 39885132, 2025). "Because the tumours themselves were no longer sensitive to IFNγ, we reasoned that IFNγ was acting on other cells." (PMID 39746898, 2025). "Tumour-intrinsic IFNG expression upregulated HLA-ABC and increased FAS and PD-L1 in three out of four conditions, with similar effects in pre-sort and enriched cells, indicating that even low expression levels can trigger tumour-wide marker upregulation." (PMID 41366257, 2025). "Despite these data were not related to an increased IFNG mRNA expression in tumor tissues, an activation of the canonical IFN-γ signaling pathway was demonstrated with an increased Stat1 phosphorylation and ISG15 expression." (PMID 40393975, 2025). "In contrast, IFNγ stimulation significantly increased TAM CXCL9 expression, with the greatest upregulation evident in Ly6C+MHC-II+ mdTAM, mirroring the effects on anti-PD-L1-treated tumours in vivo." (PMID 40523200, 2025). "Tumor cell killing and IFNγ secretion did not correlate with the EGFR expression levels of the different cell lines." (PMID 41341587, 2025). "By secreting large amounts of pro-inflammatory cytokines IFNγ and IL12, which have anti-tumor activity, M1 macrophages incite NK cell and cytotoxic T cell infiltration and activation in the tumor site, indicating an indirect mechanism of stopping the spread of cancer." (PMID 41019045, 2025). "Furthermore, H-151 not only inhibited the p-STING/p-IRF3 axis but also significantly reduced the expression of T cell infiltration and activation markers (CD3D and CD69) as well as anti-tumor factors (GZMB, IFNγ, and TNFα)." (PMID 40846839, 2025). "IFNγ-driven activation of M1 macrophages induces the ability of present antigens, activates CD8+ T cell proliferation, stimulates their effector functions, and brings CD8+ T and NK cells into the tumor." (PMID 40438186, 2025). "By inducing immediate tumor reduction, expanding effector and memory CD4 + and CD8+ T cell populations, and enhancing interferon-gamma and granzyme B activity, it primes the immune system to eliminate residual micrometastatic disease and reduces the risk of recurrence." (PMID 40115081, 2025). "Not surprisingly, the anti-tumor effect of IFNγ+Zole group was significantly weaker than the Nano-IFNγ/Zole in gel-treated group." (PMID 39776793, 2025). "Previous studies have shown that IFNγ can induce tumor stemness, prompting us to explore whether high UCK2 expression drives or results from cancer stemness mediated by IFNγ." (PMID 39931080, 2025).